HDAC3 (histone deacetylase 3)
Description:
Histone deacetylase that catalyzes the deacetylation of lysine residues on the N-terminal part of the core histones (H2A, H2B, H3 and H4), and some other non-histone substrates. Histone deacetylation gives a tag for epigenetic repression and plays an important role in transcriptional regulation, cell cycle progression and developmental events. Histone deacetylases act via the formation of large multiprotein complexes, such as N-Cor repressor complex, which activate the histone deacetylase activity. Participates in the BCL6 transcriptional repressor activity by deacetylating the H3 'Lys-27' (H3K27) on enhancer elements, antagonizing EP300 acetyltransferase activity and repressing proximal gene expression. Acts as a molecular chaperone for shuttling phosphorylated NR2C1 to PML bodies for sumoylation (By similarity). Contributes, together with XBP1 isoform 1, to the activation of NFE2L2-mediated HMOX1 transcription factor gene expression in a PI(3)K/mTORC2/Akt-dependent signaling pathway leading to endothelial cell (EC) survival under disturbed flow/oxidative stress. Regulates both the transcriptional activation and repression phases of the circadian clock in a deacetylase activity-independent manner (By similarity). During the activation phase, promotes the accumulation of ubiquitinated BMAL1 at the E-boxes and during the repression phase, blocks FBXL3-mediated CRY1/2 ubiquitination and promotes the interaction of CRY1 and BMAL1 (By similarity). The NCOR1-HDAC3 complex regulates the circadian expression of the core clock gene BMAL1 and the genes involved in lipid metabolism in the liver (By similarity). Also functions as a deacetylase for non-histone targets, such as KAT5, MEF2D, MAPK14, RARA and STAT3. Serves as a corepressor of RARA, mediating its deacetylation and repression, leading to inhibition of RARE DNA element binding. In association with RARA, plays a role in the repression of microRNA-10a and thereby in the inflammatory response. In addition to protein deacetylase activity, also acts as a protein-lysine deacylase by recognizing other acyl groups: catalyzes removal of (2E)-butenoyl (crotonyl), lactoyl (lactyl), 2-hydroxyisobutanoyl (2-hydroxyisobutyryl) and isonicotinyl acyl groups from lysine residues, leading to protein decrotonylation, delactylation, de-2-hydroxyisobutyrylation and deisonicotinylation, respectively. Catalyzes decrotonylation of MAPRE1/EB1. Mediates delactylation NBN/NBS1, thereby inhibiting DNA double-strand breaks (DSBs) via homologous recombination (HR).
Synonyms: HD3; RPD3; RPD3-2; KDAC3
Tractability: Small molecule: an approved drug acts on it; a structure with a bound ligand is known; a high-quality ligand is known; it belongs to a druggable protein family. Antibody: its Gene Ontology location is reachable by antibodies, with high confidence. PROTAC: it is named in the literature on targeted protein degradation; UniProt records ubiquitination sites on it; ubiquitination databases record sites on it; its protein half-life has been measured; a small molecule that binds it is known. Other modalities: an approved drug acts on it.
Target class: Eraser; HDAC class I; Epigenetic regulator; Histone deacetylase
Chemical probes: FK228 (high quality), JPS016, RGFP966 (high quality), XZ9002, YX968 (high quality), pandacostat
Gene: Protein-coding gene on chromosome 5 (141,620,778 to 141,636,867, reverse strand). Ensembl gene ENSG00000171720.
Subcellular location: Nucleus; Chromosome; Cytoplasm; Cytoplasm, cytosol
Subcellular location (Human Protein Atlas): Nucleoplasm; Cytosol; Golgi apparatus
Pathways (Reactome):
Signal Transduction: NOTCH1 Intracellular Domain Regulates Transcription; NR1H3 & NR1H2 regulate gene expression linked to cholesterol transport and efflux; Regulation of PTEN gene transcription; STAT3 nuclear events downstream of ALK signaling; p75NTR negatively regulates cell cycle via SC1
Disease: Constitutive Signaling by NOTCH1 HD+PEST Domain Mutants; Constitutive Signaling by NOTCH1 PEST Domain Mutants; HCMV Early Events
Gene expression (Transcription): MLL4 and MLL3 complexes regulate expression of PPARG target genes in adipogenesis and hepatic steatosis; Notch-HLH transcription pathway; RUNX2 regulates osteoblast differentiation
Developmental Biology: Activation of anterior HOX genes in hindbrain development during early embryogenesis; Differentiation of naive CD4+ T cells to T helper 2 cells (Th2 cells); Transcriptional regulation of white adipocyte differentiation
Cellular responses to stimuli: Cytoprotection by HMOX1; Heme signaling
Circadian clock: Expression of BMAL (ARNTL), CLOCK, and NPAS2; RORA,B,C and NR1D1 (REV-ERBA) regulate gene expression
Metabolism: PPARA activates gene expression; Regulation of lipid metabolism by PPARalpha
Chromatin organization: HDACs deacetylate histones
Metabolism of proteins: Association of TriC/CCT with target proteins during biosynthesis
Organelle biogenesis and maintenance: Transcriptional activation of mitochondrial biogenesis
Gene Ontology:
Molecular function: chromatin binding; cyclin binding; enzyme binding; histone deacetylase activity; histone deacetylase activity, hydrolytic mechanism; histone deacetylase binding; histone decrotonylase activity; histone isonicotinyllysine deisonicotinylase activity; NF-kappaB binding; protein binding; protein de-2-hydroxyisobutyrylase activity; protein decrotonylase activity; protein lysine deacetylase activity; protein lysine delactylase activity; transcription corepressor activity; transcription corepressor binding; DNA-binding transcription factor binding; chromatin DNA binding; DNA binding
Biological process: cellular response to fluid shear stress; DNA repair-dependent chromatin remodeling; establishment of mitotic spindle orientation; negative regulation of DNA-templated transcription; negative regulation of JNK cascade; negative regulation of myotube differentiation; negative regulation of transcription by RNA polymerase II; positive regulation of ferroptosis; positive regulation of protein import into nucleus; positive regulation of protein phosphorylation; positive regulation of TOR signaling; positive regulation of transcription by RNA polymerase II; protein deacetylation; regulation of protein stability; spindle assembly; chromatin organization; circadian regulation of gene expression; negative regulation of apoptotic process; negative regulation of transcription initiation by RNA polymerase II; positive regulation of cold-induced thermogenesis; positive regulation of protein ubiquitination; regulation of circadian rhythm; cornified envelope assembly; epidermis development; establishment of skin barrier; and 3 more
Cellular component: chromosome; cytoplasm; cytosol; histone deacetylase complex; mitotic spindle; nucleoplasm; nucleus; transcription repressor complex; chromatin
Genetic constraint (gnomAD): Loss-of-function variants: 21 observed, 65.36 expected, observed/expected ratio (o/e) 0.32, 90% interval 0.23 to 0.46. The upper end of that interval is the gene's LOEUF score, 0.46, which puts it in group 2 of 6, group 1 being the genes least tolerant of losing a copy. Missense variants: 270 observed, 587.57 expected, observed/expected ratio (o/e) 0.46, 90% interval 0.41 to 0.51. Synonymous variants: 198 observed, 219.56 expected, observed/expected ratio (o/e) 0.9, 90% interval 0.8 to 1.01.
Homologues: Orthologues: chimpanzee HDAC3 (100% identical), dog HDAC3 (100% identical), guinea pig HDAC3 (100% identical), macaque HDAC3 (100% identical), rabbit HDAC3 (100% identical), mouse Hdac3 (99% identical), pig HDAC3 (99% identical), rat Hdac3 (99% identical), tropical clawed frog hdac3 (96% identical), Caenorhabditis elegans hda-2 (49% identical). Paralogues in human: HDAC1 (60% identical), HDAC2 (59% identical), HDAC8 (36% identical), HDAC5 (26% identical), HDAC9 (25% identical), HDAC4 (25% identical), HDAC7 (24% identical), HDAC6 (19% identical), HDAC11 (18% identical), HDAC10 (11% identical).
Diseases named in the same sentence as HDAC3 in open-access papers:
HDAC3 is named in the same sentence as 298 diseases in open-access papers, as found by Europe PMC text mining. Sharing a sentence is not in itself a finding about the gene and the disease. The quoted sentences say what the papers report.
breast cancer (77 papers, 2006 to 2025). A primary or metastatic malignant neoplasm involving the breast. "Induced cytoplasmic expression of HDAC3 has been associated with brain metastasis in breast cancer patients." (PMID 40165290, 2025). "Direct repression or inactivation of HDAC7 through HDAC1 and HDAC3 inhibition downregulates multiple super‐enhancers (SEs) and SE‐associated oncogenes, suppressing cancer stem cell phenotypes in breast cancer." (PMID 38827027, 2024). "For instance, while one report demonstrated that Hdac3 ablation promoted degradation of Esr1 mRNA (i.e. the gene encoding ERα) in breast cancer cells, others have shown that HDAC3 inhibition promotes Esr1 expression." (PMID 39261913, 2024). "The upregulated levels of HDAC1 and HDAC3 are significantly associated with ERα and PR protein levels in 40% and 44% of breast cancer cases, respectively." (PMID 35453496, 2022). "Several studies have shown that HDAC3 is associated with the progression of various cancers and may be a key factor in the progression of breast cancer, colorectal cancer, and pancreatic cancer metastasis." (PMID 36770884, 2023). "However, the regulatory mechanism underlying HDAC3 activity and phosphorylation in the development of breast cancer still remains obscure." (PMID 31430896, 2019). "A previous study examined the expression of HDAC3 in 145 patients with ductal breast cancer by tissue microarray and showed that HDAC3 expression was associated with clinicopathological factors and the prognostic significance of breast cancer in these patients." (PMID 31430896, 2019). "The findings pertaining to the role of HDAC3 in breast cancers differing in ERα status provide worthwhile information on the clinical relevance of the association among these proteins and the development of new therapeutic and prevention strategies against ERα-positive breast cancer." (PMID 32455774, 2020). "Thus, whether HDAC3 is specifically associated with brain metastasis, or is associated with multiple organ metastases in breast cancer patients requires further study." (PMID 32686908, 2020). "Our results indicate that GPS2 deletion in MCF-7 breast cancer cells leads to increased HDAC3 ubiquitination and dismissal from most of its genomic locations, including both repressed and activated gene targets." (PMID 40305047, 2025). "As Dicer is an RNase that suppresses metastasis, geminin facilitates breast cancer cell metastasis via the geminin/HDAC3/FOXO3/Dicer pathway." (PMID 40003882, 2025). "In many types of tumors, such as gastric cancer, glioma, and breast cancer, HDAC3 is often overexpressed, and its elevated levels are associated with more aggressive disease characteristics and poor patient outcomes." (PMID 40006729, 2025). "The HDAC proteins were validated by many HDAC inhibitors in the colony formation assay, and the genes HDAC2 and HDAC3 have been found to be differentially expressed in human breast cancer and strongly expressed in aggressive tumor subgroups." (PMID 38935814, 2024). "In a study, HDAC3 depletion substantially increased the migration of MDA-MB-231 metastatic breast cancer cells." (PMID 34973135, 2023). "In this study, SERPINA3 was identified to be a direct target gene of ERα, and its downregulation enhanced the expression of ankyrin repeat domain containing 11 (ANKRD11), which resulted in elevated HDAC3 activity and AI resistance in ER+ breast cancer." (PMID 37414914, 2023). "The distinguished roles of ANKRD11 in Ki67-high and -low group suggest a strong disturbance of Ki67 related pathway to ANKRD11 function and highlight the necessity of restrictive administration of HDAC3 inhibitor in luminal A breast cancer." (PMID 37414914, 2023).
breast cancer (continued). "Further mechanistic insights revealed the down-regulation of HDAC2 and HDAC3 and enhanced levels of H3K4Me3 (trimethylated lysine 4 of histone 3) in the promoter region of p21 in both breast cancer cell lines." (PMID 36765652, 2023). "Data retrieved from bc-GenExMiner v4.9 even indicates a slight decrease of HDAC3 in ER− breast cancer compared with ER+ subtype." (PMID 37414914, 2023). "And it is even interesting to know that upregulated cytoplasmic HDAC3 is an independent prognostic factor for brain metastasis-free survival of breast cancer patients." (PMID 37414914, 2023). "Additionally, overexpression of the secreted isozyme of HDAC3 has been associated with reduced expression of p21 in colorectal cancer, and HDAC3 has been found to play a role in reducing cell proliferation in breast cancer through its interaction with the CREB protein." (PMID 38139766, 2023). "Among these, epigenetic modifiers that were previously implicated in breast cancer cell fitness, such as PRMT5, HDAC3, NPM1 were depleted in MDA-MB-231 cells serving as positive controls." (PMID 35973998, 2022). "As a transcriptional inhibitor of VEGF gene, Kruppel-like Factor 4 (KLF4) recruits HDAC2 and HDAC3 to the VEGF gene promoter for suppressing VEGF gene transcription in breast cancer." (PMID 34307380, 2021). "HDAC2 enables the motility of breast cancer cells by upregulating Matrix Metalloproteinase 2 (MMP2) and N-cadherin and HDAC3 associates with Epidermal Growth Factor Receptor (EGFR) and c-Src to promote breast cancer cell invasion." (PMID 33803458, 2021). "HDAC1, HDAC2, and cytoplasmic HDAC3 all displayed typical oncogenic characteristics and were independent prognostic factors for the overall survival of breast cancer patients." (PMID 32686908, 2020). "Next, to re-confirm the results shown with the involvement of HDAC1 and HDAC3 in breast cancer cell death, we observed the morphological changes using a phase contrast microscope." (PMID 32455774, 2020). "In multivariate Cox regression analysis, HDAC1, HDAC2, or cytoplasmic HDAC3 was still an independent prognostic factor for the overall survival of breast cancer patients after correction for tumor size, histological grade, lymph node status, ER and PR." (PMID 32686908, 2020). "Cytoplasmic HDAC3 is an independent prognostic factor for the overall survival and brain metastasis‐free survival of breast cancer patients." (PMID 32686908, 2020). "It has also been reported that HDAC3 inhibition decreases the stability of the estrogen receptor-α (ERα) mRNA in ERα-positive human breast cancer (MCF-7) cells." (PMID 32455774, 2020). "The expression of GATA-1 has been shown to be upregulated in breast cancer and repress the E-cadherin transcription by binding to the E-cadherin promoter and recruiting HDAC3/4." (PMID 31783675, 2019). "HDAC3 was recently shown to exhibit high expression in breast cancer, and its expression was significantly correlated with poor overall survival." (PMID 31430896, 2019).